RN7SL241P (RNA, 7SL, cytoplasmic 241, pseudogene)
Gene: Miscellaneous RNA gene on chromosome 10 (30,366,064 to 30,366,299, reverse strand). Ensembl gene ENSG00000239625.
Homologues: Orthologues: chimpanzee Metazoa_SRP (99% identical), pig Metazoa_SRP (61% identical), macaque Metazoa_SRP (57% identical). Paralogues in human: RN7SL214P (90% identical), RN7SL736P (90% identical), RN7SL536P (89% identical), Metazoa_SRP (89% identical), RN7SL106P (89% identical), RN7SL238P (89% identical), RN7SL469P (89% identical), RN7SL495P (89% identical), RN7SL545P (89% identical), RN7SL673P (89% identical), RN7SL759P (89% identical), RN7SL628P (88% identical), and 709 more.